ENG (endoglin)
Diseases named in the same sentence as ENG in open-access papers (continued):
Sharing a sentence is not in itself a finding about the gene and the disease.
cancer (continued). "In contrast to several studies exploring endoglin in terms of endothelial cells and angiogenesis, little is known about the role of endoglin in cancer cells, although the expression of endoglin has already been detected in cancer cells of different origin." (PMID 26712792, 2015). "On the other hand, many human cancer cells express endoglin as its expression has been detected in different carcinoma and sarcoma cell lines." (PMID 26712792, 2015). "Several molecular angiogenic markers that are overexpressed in tumors, such as integrin, particularly αvβ3, endoglin, and vascular endothelial growth factor receptor 2 are potential targets for early cancer detection." (PMID 25654118, 2015). "For example, biomarker analyses from cancer patients treated with escalating doses of TRC105 revealed significant increases of soluble endoglin (sEnd) after TRC105 administration." (PMID 24994097, 2014). "Endoglin has previously been shown to be an important suppressor of human PCa cell invasion and metastasis, and its expression is lost with cancer progression." (PMID 23967299, 2013). "In multiple cancers including PCa, endoglin is overexpressed in endothelial cells of the microvasculature and is associated with angiogenesis." (PMID 23967299, 2013). "Several studies have suggested that CD105/endoglin is a specific marker of neovascularization in several cancer processes." (PMID 24040306, 2013). "The role of endoglin in cancer is complex, given differential expression and function across cell types." (PMID 23967299, 2013). "Several studies have suggested that endoglin is a specific marker of neovascularization in various cancer types." (PMID 22069717, 2011). "The measure of serum endoglin appears to provide important prognostic information in cancer patients." (PMID 15743520, 2005). "Indeed, purified THSD7A was able to rescue filopodia defects in both endoglin-KD cancer cells and exosome-inhibited neurons." (PMID 41532547, 2026). "Indeed, we found that endoglin-KD cancer cells had defects in not only filopodia formation but also in 3D migration and metastasis to chick embryo chorioallantoic membranes." (PMID 41532547, 2026). "Based on the observed decreases in THSD7A expression in SEVs from endoglin-KD cancer cells and the role of endoglin as a co-receptor that traffics through endosomes, we hypothesized that endoglin may alter the trafficking of THSD7A to SEVs/exosomes." (PMID 41532547, 2026). "Cancer cells seem to sometimes use endoglin and ALK1 to trap BMP-9 protein: sENG binds to BMP-9 with high affinity and thereby blocks the type II receptor binding site on BMP-9, resulting in ALK1-mediated binding of BMP-9 to the cell surface but without any signal transduction being initiated." (PMID 41378712, 2025). "CD105+ (endoglin) cells were detected at the tumoroid periphery, and these may represent either endothelial or cancer cells, some of which are Ki67 positive." (PMID 40957946, 2025). "VEGFA, PDGFRB, ANGPTL4 and ENG have been shown to play major roles in angiogenesis and vascular homeostasis, not only in physiological regeneration but also in most pathological angiogenic processes such as cancer." (PMID 38882056, 2024). "Various proangiogenic factors that serve as potential biomarkers in cancer therapy are VEGF, bFGF, IL-8, PDGF, MMPs, endoglin, tissue factor, and hypoxia tissue factor and among them, the important angiogenesis biomarkers explored for cancer therapy are discussed in the following subsection." (PMID 38213742, 2024). "Interestingly, endoglin was found to be positively correlated with both the growth of malignant tumors and the growth of solid tumors." (PMID 35203627, 2022). "Targeting endoglin might serve as a potential alternative treatment to control angiogenesis, leading to metastasis and limiting cancer progression." (PMID 35203627, 2022).
cancer (continued). "In humans, it has been hypothesized that individuals with HHT may be protected against life-limiting cancers due to limited angiogenesis, since endoglin and ALK1 are proangiogenic factors." (PMID 33925423, 2021). "These cells express endoglin mostly in the context of complex TGF-β-regulated pathologic lesions like cancer, cardiovascular diseases, and fibrosis, suggesting that endoglin may be employed to target various pathologic conditions for therapy or imaging." (PMID 33946583, 2021). "Therefore, treatment with GN and rGO, resulting in decreased endoglin expression, can stimulate cell adhesion and, consequently, leads to the reduction of the ability of cancer cell migration." (PMID 33419226, 2021). "High levels of soluble endoglin have been found in patients with preeclampsia and in some types of cancer, although there is controversy about its function in tumors, since in some cases it seems to have an antitumor role and it is associated with worse prognosis in others." (PMID 33800564, 2021). "Both endothelial cells and cancer cells release soluble endoglin." (PMID 33809908, 2021). "In conclusion, the presence of Endoglin in immune cells should help to increase/provide the treatments and knowledge toward processes leading to cancer and immune escape as well as pathologies depending on vascular dysfunction associated with inflammatory processes." (PMID 33287465, 2020). "The expression of endoglin on a variety of cells increases the potential for TRC105 to be used as a cancer therapy and might even extend beyond the field of oncology, looking, for example, at fibrotic diseases." (PMID 33375670, 2020). "Endoglin is essentially expressed on endothelial cells that form the arteries, veins, and capillaries and plays an important role in cardiovascular diseases, angiogenic processes, and cancer." (PMID 32434528, 2020). "For this reason, endoglin has become a promising target for the antiangiogenic treatment of cancer." (PMID 31540324, 2019). "CD105/endoglin is also expressed by certain types of cancer and stem cells." (PMID 31340569, 2019). "Furthermore, as part of the TGFβ receptor complex, ENG was already investigated in some preclinical and clinical studies dealing with anti-cancer therapies." (PMID 28859090, 2017). "Nevertheless, drugs for cancer indications are rarely used as monotherapy, therefore targeting of endoglin and/or BMP9 may still be pursued as partners in combinatorial treatments." (PMID 27741515, 2016). "On the other hand, as endoglin has been recently proposed as a target for novel anti-cancer treatments, the evidence of a high number of endoglin-positive vessels in BM may also open novel therapeutic perspectives for the treatment of these tumors." (PMID 24699047, 2014). "Conversely, there are data that cancer growth is reduced in endoglin +/- mice." (PMID 24354965, 2013). "This feature makes endoglin a promising target for antiangiogenic cancer therapy." (PMID 21170488, 2010). "Indeed, VE-cadherin and Endoglin antibodies have been investigated for their anti-cancer efficacy." (PMID 39518030, 2024). "Furthermore, through expression of ligands for Notch and Bmp7, tuft cells could target Notch1/3 and Endoglin (Eng) on endothelial and smooth muscle cells to promote cancer progression through promotion of angiogenesis." (PMID 37386128, 2023). "The inhibition of endoglin may be beneficial for cancer treatment." (PMID 35409247, 2022).
cancer (continued). "Interestingly, the levels of Sol-ENG increase after treatment with TRC105 in cancer patients, which may reflect the direct anti-angiogenic effects of the drug." (PMID 33804796, 2021). "Moreover, INHA itself was dependent on TGFBR3 and ENG/CD105 in multiple cancer types." (PMID 33819300, 2021). "In this review we propose that endoglin (CD105) may be a useful target of this strategy since it is involved in the three main processes involved in the generation of the TME: angiogenesis, inflammation, and cancer-associated fibroblast (CAF) accumulation." (PMID 33800564, 2021). "Therefore, it might be of great interest to investigate the endoglin-dependent TEM of T-cells in cancer patients." (PMID 32059544, 2020). "It has been found that the silencing of ENG by hypermethylation in the promoter region could be reactivated by demethylation that can reduce colony formation efficiency and suppress invasion efficiency and tumorigenicity of cancer cells." (PMID 28178989, 2017). "Thus, at the overall tissue level, endoglin is often overexpressed in cancer." (PMID 23967299, 2013). "In addition, endoglin is expressed minimally in benign tissues but strongly in malignant tumors." (PMID 22069717, 2011). "In cancer cells, we identified endoglin as a key SEV cargo and molecular regulator of this process, controlling filopodia formation, cell migration, and metastasis of cancer cells via SEVs." (PMID 41532547, 2026). "We further found that both cancer cell and neuronal SEVs carry THSD7A and that add-back of purified THSD7A is sufficient to rescue filopodia defects of both endoglin-KD cancer cells and exosome-inhibited neurons." (PMID 41532547, 2026). "Both substances contribute to stimulate CAF endoglin expression and therefore negatively modulate the TGFβ1/SMAD2/3 pathway in cancer cells by decreasing extracellular TGFβ1 levels." (PMID 40384860, 2025). "Our results evidenced that the expression of cancer stem cell surface markers, including EPCAM, CSF3R, CD34, CD96 and ENG, were significantly different." (PMID 38977778, 2024). "The endoglin neutralizing antibody (TRC105; carotoximab), after being tested in many preclinical cancer models, has entered clinical studies (phase I–III) for cancer patients as mono- or combination therapy." (PMID 36769077, 2023). "CD105/Endoglin, a type I transmembrane protein belonging to the transforming growth factor (TGF) beta receptor family, is regarded as a cancer angiogenic marker." (PMID 36038950, 2022). "CD105 (endoglin) is a TGF-beta coreceptor and activates endothelial cells in healthy tissues and cancer." (PMID 35044512, 2022). "Among Roquin2 targets, we chose four angiogenic genes (ENG, EDN1, VEGFB, and PDGFC) based on two criteria: 1) they are commonly downregulated in different types of cancer cells; and 2) they are among the most affected genes by Roquin2." (PMID 34345214, 2021). "Inhibins are biomarkers in a subset of cancers and utilize the coreceptors betaglycan (TGFBR3) and endoglin (ENG) for physiological or pathological outcomes." (PMID 33819300, 2021). "Our findings provide significant new information on the specific cancers impacted by the genes investigated here, INHA, INHBA, INHBB, ENG and TGFFBR3, and shed light on potential functional dependencies." (PMID 33819300, 2021). "Targeting endoglin and the VEGF pathway concurrently improves treatment in vitro and appears to reverse resistance in refractory cancer patients." (PMID 35010954, 2021). "OC-X treatments also caused surge upregulation of several important biomarkers within each cancer progression stage, including UCP1, NOSTRIN, SCGB3A1, ENG, EPAS1, SFTPD, and BMP4." (PMID 34069906, 2021). "Gene signatures from our analysis reveal robust relationships between INHA, ENG, and TGFBR3 and other established cancer biomarkers." (PMID 33819300, 2021). "Namely, CLEC14A, CD93, endoglin, and ANTXR1 (alias TEM8) have shown to be overexpressed in several cancers." (PMID 34770976, 2021).
cancer (continued). "It is clear that multiple cells can express endoglin, mainly in a TGF-β environment, such as cancer, in which both CAFs and some immune cells express endoglin." (PMID 32059544, 2020). "In line with this, both TRIM21 and endoglin appear to induce the epithelial–mesenchymal transition (EMT), a key process in cancer development." (PMID 31540324, 2019). "Several reports have shown the involvement of TRIM21 in cancer development, a characteristic shared by other TRIM family members and, interestingly, by endoglin." (PMID 31540324, 2019). "Using the model of cancer stem-like cell (CSCs) generated from HCV-infected primary and transformed human hepatocytes, it was shown that endoglin is upregulated (250-fold) in sphere-forming cells compared to primary hepatocytes." (PMID 30563158, 2018). "We found that SPARCL1, ENG, TAL1, ATP8A2 and HOXA9 were down-regulated in 99, 94, 89, 65 and 49% of the 82 cancer samples." (PMID 28178989, 2017). "There are currently several anti-cancer drugs targeting TGF-β family signaling, including dalantercept and PF-03446962 blocking ALK1, and TRC-105 neutralizing endoglin, in Phase II/III of clinical development for a range of indications." (PMID 27741515, 2016). "Co-expression of endoglin and ActRIIA, when expressed on PC3 or DU-145 cells, has shown suppressed cancer cell invasion, while co-expression of endoglin with ActRIIB, BMP and TGFβ does not exhibit this effect." (PMID 25560921, 2014). "As endoglin seemed unlikely to directly induce filopodia formation and is not present in neurons, we performed quantitative proteomics of control and endoglin-KD SEVs and identified the transmembrane ECM protein THSD7A as regulated in cancer cell SEVs by endoglin." (PMID 41532547, 2026). "ENG, a TGF‐β superfamily coreceptor, is essential for smooth muscle cell specification, contributing to vascular integrity, and its expression is often upregulated in myofibroblasts in settings of tissue injury, fibrosis, and cancer." (PMID 40644310, 2025). "In cancer cells, but not ECs, soluble endoglin (sENG) can modulate BMP-9 signaling leading to sENG-mediated inhibition of BMP-9-induced apoptosis." (PMID 41378712, 2025). "In the present study three key genes in UCEC include Endoglin, GNG4 and epithelial cell transforming 2 (ECT2) identified, therefore enhancing our comprehension of UCEC and broadening insights into the prognosis for this cancer type." (PMID 39552710, 2024). "Therefore, we investigated SCC endoglin expression and function in three types of SCCs; head and neck (HNSCC), esophageal (ESCC) and vulvar (VSCC) cancers." (PMID 37396898, 2023). "APC (P), BRCA2 (P), BUB1B (LP), ENG (LP) and MSH6 (P) were identified in patients with cancer." (PMID 36896836, 2023). "Endoglin is an endothelial cell membrane glycoprotein (also known as CD105) that actively participates in blood vessel development and is another promising target in cancer therapy." (PMID 35456655, 2022). "Finally, we also investigated the stem cell marker, CD105 (endoglin), a coreceptor for TGF-β highly expressed in proliferating endothelial cells and a marker for cancer stem cells in ccRCC." (PMID 36275794, 2022). "Moreover, GN and rGOs decrease the expression of endoglin (CD105) and probably provide an increase in cell adhesion, consequently reducing cancer cell migration." (PMID 33419226, 2021). "Both ENG and TGFBR3 were predictive in other cancer types as well." (PMID 33819300, 2021). "Endoglin is an essential part of the transforming growth factor (TGF)-beta receptor complex, which is involved in the formation of new blood vessels in many diseases, including cancers." (PMID 32316521, 2020).
cancer (continued). "Clinical trials have recently begun on a chimeric IgG1 anti-CD105 monoclonal antibody (TRC105) that binds human endoglin with high avidity, indicating that CD105 might be a promising anti-angiogenic target of cancer therapy." (PMID 32722476, 2020). "The expression of Endoglin in intratumoral Tregs (CD4+/CD25+/Foxp3+) was confirmed/shown in a recent study, which focused on the efficiency of TRC105/PD1 antibody treatment in different cancer settings." (PMID 33287465, 2020). "CD105, also referred to as ENG, END, FLJ41744, HHT1, ORW, and ORW1, predominantly participates in angiogenesis, making it an important protein for tumor growth and survival and the metastasis of cancer cells to other locations in the body." (PMID 31870454, 2019). "A number of immunotoxins have been constructed for antiangiogenic therapy targeting a biomarker of proliferation-dependent pathologies, such as CD105 (endoglin), a TGF-β co-receptor highly expressed in proliferating endothelial cells of the new vasculature in various cancer types." (PMID 25647575, 2015). "Moreover, in cancer cells, the secretion of THSD7A-containing exosomes, filopodia formation, cell migration, and metastatic colony formation were regulated by a growth factor receptor known as endoglin." (PMID 41532547, 2026). "ENG staining was negative on cancer cells, granulocytes, and macrophages." (PMID 40644310, 2025). "Notably, we demonstrated that ENG+ CAFs, WT1+ CAFs, and CAPs shared phenotypic characteristics with mesenchymal populations in the healthy developing pancreas, whereas LRRC15+ CAFs represented a cancer-specific phenotype." (PMID 40215177, 2025). "Molecular features of endoglin make it a reliable biomarker that may contribute malignant phenotypes in cancer to either an oncogenic or a non-oncogenic phenotype on the cell context." (PMID 39552710, 2024). "Thus, ENG DNA methylation CpGs, specifically CpG island cg14185922, are potential prognostic markers that could be important in discriminating BRCA cancer from normal samples." (PMID 39247590, 2024). "In cancer, in particular, endoglin may contribute to either an oncogenic or a non-oncogenic phenotype depending on the cell context." (PMID 33804796, 2021). "However, the effect of increased endoglin expression, described in pathologies such as cancer, on the function of ECs and angiogenesis has not been deeply studied." (PMID 31897911, 2020). "Furthermore, endoglin and/or THSD7A could serve as potential targets for anti-cancer therapies." (PMID 41532547, 2026). "Given our new findings that endoglin is a key regulator of filopodia via regulating THSD7A trafficking to SEVs, an important future direction could be to test the contribution of THSD7A to endoglin-dependent phenotypes, including angiogenesis and cancer metastasis." (PMID 41532547, 2026). "To understand what factors influence sENG function in different cells, here we investigate the effect of sENG on BMP9 signaling in different non-endothelial cells including cancer cells, and whether cell surface ENG and ALK1 expression influence the cellular response to sENG and BMP9." (PMID 37095146, 2023). "It is worth investigating the regulatory role of ENG and the potential clinical significance of CD in BRCA or triple-negative breast cancer (TNBC), as well as in other types of cancer." (PMID 39247590, 2024).